ARHGEF26 (Rho guanine nucleotide exchange factor 26)
Description:
Activates RhoG GTPase by promoting the exchange of GDP by GTP. Required for the formation of membrane ruffles during macropinocytosis. Required for the formation of cup-like structures during trans-endothelial migration of leukocytes. In case of Salmonella enterica infection, activated by SopB, which induces cytoskeleton rearrangements and promotes bacterial entry.
Synonyms: SGEF; HMFN1864; DKFZP434D146; CSGEF
Tractability: Antibody: the Human Protein Atlas places it where antibodies can reach. PROTAC: ubiquitination databases record sites on it; its protein half-life has been measured.
Gene: Protein-coding gene on chromosome 3 (154,121,003 to 154,257,827, forward strand). Ensembl gene ENSG00000114790.
Subcellular location: Cell projection, ruffle
Subcellular location (Human Protein Atlas): Plasma membrane; Cytosol; Nucleoplasm
Pathways (Reactome):
Signal Transduction: CDC42 GTPase cycle; G alpha (12/13) signalling events; NRAGE signals death through JNK; RHOG GTPase cycle
Gene Ontology:
Molecular function: protein binding; guanyl-nucleotide exchange factor activity
Biological process: regulation of actin cytoskeleton organization
Cellular component: plasma membrane; cytosol; ruffle
Genetic constraint (gnomAD): Loss-of-function variants: 57 observed, 82.56 expected, observed/expected ratio (o/e) 0.69, 90% interval 0.56 to 0.86. The upper end of that interval is the gene's LOEUF score, 0.86, which puts it in group 3 of 6, group 1 being the genes least tolerant of losing a copy. Missense variants: 1,233 observed, 1,105.3 expected, observed/expected ratio (o/e) 1.12, 90% interval 1.06 to 1.17. Synonymous variants: 500 observed, 437.83 expected, observed/expected ratio (o/e) 1.14, 90% interval 1.06 to 1.23.
Homologues: Orthologues: chimpanzee ARHGEF26 (99% identical), pig ARHGEF26 (90% identical), macaque ARHGEF26 (90% identical), rat Arhgef26 (87% identical), rabbit ARHGEF26 (87% identical), mouse Arhgef26 (87% identical), dog ARHGEF26 (77% identical), guinea pig ARHGEF26 (71% identical), tropical clawed frog arhgef26 (67% identical), Caenorhabditis elegans ephx-1 (28% identical). Paralogues in human: ARHGEF16 (37% identical), ARHGEF5 (24% identical), ARHGEF19 (22% identical), NGEF (22% identical), ARHGEF15 (22% identical), ARHGEF35 (6% identical).
Diseases named in the same sentence as ARHGEF26 in open-access papers:
ARHGEF26 is named in the same sentence as 22 diseases in open-access papers, as found by Europe PMC text mining. Sharing a sentence is not in itself a finding about the gene and the disease. The quoted sentences say what the papers report.
glioma (6 papers, 2017 to 2022). A benign or malignant brain and spinal cord tumor that arises from glial cells (astrocytes, oligodendrocytes, ependymal cells). "Likewise, the reduction of ARHGEF26 sensitizes cells to chemotherapeutic agents and suppresses the colony formation of glioma cells." (PMID 35565298, 2022). "Glioblastoma tumors overexpress ARHGEF26, which favors glioma invasion." (PMID 34301206, 2021).
breast carcinoma (3 papers, 2012 to 2022). "A novel signaling pathway involving ARHGEF26 regulates invadopodia disassembly in breast cancer cells." (PMID 34301206, 2021).
colitis (1 paper, 2021). Inflammation of the colon. "Given our finding that Arhgef26-/- mice have substantially reduced inflammation, we were surprised to find that bacterial burden was not affected in the large intestine at late time points during the colitis model." (PMID 34242364, 2021). "Using the murine colitis model, we examined whether ARHGEF26 promoted inflammation and pathology by infecting wild-type and Arhgef26-/- mice following streptomycin pretreatment." (PMID 34242364, 2021). "In contrast, SopB and SopE2 were not required for the impacts of Arhgef26 deletion on colitis." (PMID 34242364, 2021). "The fourth hypothesis is that differences in Arhgef26 expression across the different gastrointestinal compartments could lead to the observation that S. Typhimurium burden is reduced in the ileum, but not the cecum or colon, at four days post infection in the colitis model." (PMID 34242364, 2021). "Finally, our results studying IL-8 in HeLa cells and inflammation in the murine colitis model were also unexpected, as no report has shown ARHGEF26 may promote proinflammatory processes, and in fact, some have speculated that it may be involved in anti-inflammatory processes." (PMID 34242364, 2021).
coronary artery disease (1 paper, 2021). "A recent GWAS has identified ARHGEF26 as a new genetic factor for coronary artery disease risk that influences the transendothelial migration of leukocytes." (PMID 30361487, 2021).
diabetes (1 paper, 2025). "Therefore, the expression of ARHGEF26 in glomerular endothelial cells may facilitate VEGFA-induced VEGFR-2 internalization on the cell surface via macropinocytosis, thereby protecting the glomerular microvasculature in diabetes." (PMID 40690456, 2025).
endothelial dysfunction (1 paper, 2023). In vascular diseases, endothelial dysfunction is a systemic pathological state of the endothelium (the inner lining of blood vessels) and can be broadly defined as an imbalance between vasodilating and vasoconstricting substances produced by (or acting on) the endothelium. "AIDA, ARHGEF26, ADAMTS7), most are implicated in endothelial dysfunction for the first time." (PMID 36928188, 2023).
human papillomavirus infection (1 paper, 2021). "Previous work has demonstrated that the Scribble complex members DLG1 and/or SCRIB play key roles facilitating ARHGEF26 activity and RHOG activation during human papillomavirus infection, as well as in regulating epithelial junction formation, contractability, and lumen formation in 3D cysts." (PMID 34242364, 2021).
Salmonella Infections (1 paper, 2021). Infections with bacteria of the genus SALMONELLA. "Our work has also expanded understanding of ARHGEF26-mediated invasion susceptibility by demonstrating that the protein has serovar and cell line dependent roles during Salmonella infection." (PMID 34242364, 2021). "Collectively, these results identify a potential source of inter-person diversity in susceptibility to Salmonella disease and expand our molecular understanding of Salmonella infection to include a multifaceted role for ARHGEF26." (PMID 34242364, 2021). "Instead, we propose that there are multiple levels of cytokine regulation by ARHGEF26, and that this could have important implications during Salmonella infection." (PMID 34242364, 2021). "We next sought to examine whether ARHGEF26 regulates inflammation during Salmonella infection." (PMID 34242364, 2021).
cancer (5 papers, 2016 to 2021). A tumor composed of atypical neoplastic, often pleomorphic cells that invade other tissues. "ARHGEF26 activates the Rho family of RhoG and also regulates cancer cell migration." (PMID 34440281, 2021). "Although MMP1, MMP10 and PTHLH were mainly up-regulated in the 21 cancer types, the other two members GATM and ARHGEF26, were primarily down-regulated." (PMID 34301206, 2021). "Although PTHLH, MMP1 and MMP10 were mainly up-regulated in the 21 cancer types, the rest of the members GATM and ARHGEF26, were primarily down-regulated with a few exceptions." (PMID 34301206, 2021).
tumor (5 papers, 2012 to 2021). "GATM, ARHGEF26 and POU2F3 were associated with better survival, and were recognized as tumor suppressors." (PMID 34301206, 2021).
infection (1 paper, 2021). The state of being infected such as from the introduction of a foreign agent such as serum, vaccine, antigenic substance or organism. "RNAi knockdown of ARHGEF26, confirmed by qPCR (knockdown ≥40%), showed reduced proportion of LCLs with S. Typhi and S. Typhimurium uptake following infection—a phenotype similar to the protective rs993387 T-allele in LCLs." (PMID 34242364, 2021). "Following up on these in vitro studies, we found that Arhgef26 deletion restricted S. Typhimurium burden in an enteric fever model of infection." (PMID 34242364, 2021). "Together, these data reveal pleiotropic roles for ARHGEF26 during infection and highlight that many of the interactions that occur during infection that are thought to be well understood likely have underappreciated complexity." (PMID 34242364, 2021). "Considering each mouse model separately, we can conclude ARHGEF26 plays a critical, multifaceted role in enabling S. Typhimurium to utilize the SPI-1 secretion system to cause disease in both models of murine infection." (PMID 34242364, 2021). "To test this hypothesis, we utilized Arhgef26-/- C57BL/6J mice to assess the ability of S. Typhimurium to establish infection using the oral enteric fever model of infection." (PMID 34242364, 2021). "The third hypothesis is that while we observed substantially reduced inflammation at two days post infection by pathology scoring, Arhgef26-/- mice may have altered dynamics of inflammation, rather than outright ablation of inflammation." (PMID 34242364, 2021). "Infection with S. Typhi caused induction of IL-8, and levels were moderately lower in supernatants with ARHGEF26, but not with RHOG knockdown." (PMID 34242364, 2021). "Therefore, identifying the GTPase(s) that ARHGEF26 activates during infection represents an important future direction." (PMID 34242364, 2021). "Thus, at four days post infection, Arhgef26 knockout mice may have elevated inflammation that can clear out recolonizing microbes." (PMID 34242364, 2021). "While ARHGEF26 regulated SopB- and SopE-mediated S. Typhi (but not S. Typhimurium) infection of HeLa cells, the largest effect of ARHGEF26 was observed with S. Typhimurium in polarized MDCK cells through a SopB- and SopE2-independent mechanism." (PMID 34242364, 2021). "This substantially larger phenotype with infection leads us to conclude that our results are not simply consequences of lower basal levels of cytokine production following ARHGEF26 knockdown." (PMID 34242364, 2021). "We also expanded our understanding of Salmonella’s interaction with ARHGEF26, finding that S. Typhi, but not S. Typhimurium uses ARHGEF26, DLG1 (also known as SAP97) and SCRIB (also known as Scribble) for SopB- and SopE- mediated infection of HeLa cells." (PMID 34242364, 2021).
ARHGEF26 also shares sentences with these, for which no sentence is quoted: atherosclerosis (4 papers); glioblastoma (4); prostate carcinoma (3); lung carcinoma (2); aortic atherosclerosis (1); cervical cancer (1); cervical tumour (1); lung adenocarcinoma (1); non-small cell lung carcinoma (1); oral cancer (1); prostate tumors (1).